RNF180 (ring finger protein 180)
Description:
E3 ubiquitin-protein ligase which promotes polyubiquitination and degradation by the proteasome pathway of ZIC2.
Synonyms: RINES
Tractability: Antibody: UniProt predicts a signal peptide or a membrane-spanning region.
Gene: Protein-coding gene on chromosome 5 (64,165,291 to 64,372,869, forward strand). Ensembl gene ENSG00000164197.
Subcellular location: Endoplasmic reticulum membrane; Nucleus envelope
Subcellular location (Human Protein Atlas): Cytosol
Gene Ontology:
Molecular function: protein binding; ubiquitin conjugating enzyme binding; ubiquitin protein ligase activity; metal ion binding
Biological process: norepinephrine metabolic process; positive regulation of proteasomal ubiquitin-dependent protein catabolic process; serotonin metabolic process; protein polyubiquitination; protein ubiquitination
Cellular component: endoplasmic reticulum membrane; nuclear envelope
Genetic constraint (gnomAD): Loss-of-function variants: 26 observed, 39.22 expected, observed/expected ratio (o/e) 0.66, 90% interval 0.49 to 0.92. The upper end of that interval is the gene's LOEUF score, 0.92, which puts it in group 3 of 6, group 1 being the genes least tolerant of losing a copy. Missense variants: 544 observed, 552.59 expected, observed/expected ratio (o/e) 0.98, 90% interval 0.92 to 1.06. Synonymous variants: 217 observed, 201.55 expected, observed/expected ratio (o/e) 1.08, 90% interval 0.96 to 1.21.
Homologues: Orthologues: chimpanzee RNF180 (99% identical), macaque RNF180 (97% identical), pig RNF180 (88% identical), dog RNF180 (86% identical), rat Rnf180 (83% identical), mouse Rnf180 (82% identical), guinea pig RNF180 (78% identical), rabbit RNF180 (57% identical), tropical clawed frog rnf180 (40% identical), zebrafish rnf180a (25% identical). Paralogues in human: RNF166 (9% identical), RNF114 (8% identical), RNF125 (7% identical), RNF138 (7% identical).
Diseases named in the same sentence as RNF180 in open-access papers:
RNF180 is named in the same sentence as 21 diseases in open-access papers, as found by Europe PMC text mining. Sharing a sentence is not in itself a finding about the gene and the disease. The quoted sentences say what the papers report.
gastric cancer (30 papers, 2014 to 2025). A primary or metastatic malignant neoplasm involving the stomach. "This will allow for a systematic evaluation of the feasibility of the plasma RNF180 gene methylation test as a diagnostic biomarker for gastric cancer." (PMID 36703788, 2022). "In this study, Lambda, an effect index representing diagnostic test discriminatory capacity, was 1.38 (1.01, 1.75), indicating that the RNF180 gene methylation test has a relatively high diagnostic accuracy in gastric cancer diagnosis." (PMID 36703788, 2022). "There is a paucity of evidence-based medical evidence about the diagnostic effectiveness of RNF180 gene methylation in the diagnosis of gastric cancer." (PMID 36703788, 2022). "A systematic evaluation of the diagnostic value of Ring finger protein 180 (RNF180) gene methylation as a novel tumor marker for gastric cancer (GC) is required to improve the early diagnosis of gastric cancer patients." (PMID 36703788, 2022). "The methylation status of RNF180 gene has diagnostic value for gastric cancer and has the potential to be used as a new tumor marker for the diagnosis of gastric cancer in clinical practice, according to our meta-analysis results based on nine studies." (PMID 36703788, 2022). "There is growing evidence that plasma RNF180 methylation is linked to gastric cancer, and RNF180 methylation has great potential as a diagnostic and prognostic tumor marker, with promising research prospects." (PMID 36703788, 2022). "The detection of RNF180 gene methylation in plasma has a high diagnostic value for GC and is expected to be a potential biomarker for the diagnosis of gastric cancer, according to current evidence." (PMID 36703788, 2022). "Promoter methylation of RNF180 is associated with Helicobacter pylori infection and serves as a marker for gastric cancer and atrophic gastritis." (PMID 28418867, 2017). "On the basis of our previous studies, we demonstrated that the methylation of CpG-116, CpG-80, CpG+97, and CpG+102 in the RNF180 DNA promoter was significantly associated with the prognosis of gastric cancer patients." (PMID 27223257, 2016). "The loss or downregulation of RNF180 is associated with a significantly increased risk of cancer-related deaths of gastric cancer patients." (PMID 27223257, 2016). "We reported that four hypermethylated CpG islands, namely, CpG-116, CpG-80, CpG+97, and CpG+102, in RNF180 promoter were significantly associated with the postoperative overall survival of gastric cancer patients." (PMID 27223257, 2016). "Of these 45 tissues, 33 cases (73.33%) are partial methylation of RNF180 promoter, which indicates the various methylated levels of RNF180 promoter were potentially associated with gastric canceration." (PMID 24833402, 2014). "Lastly, loss or down-regulation of RNF180 was also identified to be associated with a significantly increased risk of cancer-related death of 149 gastric cancer patients." (PMID 24833402, 2014). "With this method, we found that both methylated CpG site count and location of methylated CpG sites of RNF180 promoter were negatively associated with the OS of 400 gastric cancer patients." (PMID 24833402, 2014). "Researchers demonstrated that promoter methylation of RNF180 DNA was more frequently detected in the gastric cancer tissue samples, which led to low or loss RNF180 expression in gastric cancer patients with poor overall survival (OS)." (PMID 24833402, 2014). "Thus, the findings suggest that the methylation status of the RNF180 gene has good diagnostic accuracy for gastric cancer and can be used as an effective biomarker for the disease." (PMID 36703788, 2022). "The methylation of various CpG islands in the RNF180 DNA promoter may elicit different effects on lymph node metastasis associated with gastric cancer." (PMID 27223257, 2016).
gastric cancer (continued). "Therefore, this study investigated the diagnostic value of RNF180 methylation assay for gastric cancer by systematically evaluating all relevant clinical studies in the current field, and provided a reference for the application of tumor markers for the early diagnosis of gastric cancer." (PMID 36703788, 2022). "As a tumor suppressor gene, RNF180 is significantly associated with the prognosis of patients with gastric cancer (GC) and can inhibit the proliferation, invasion, and migration of GC cells." (PMID 33082325, 2020). "Thus, RNF180 PM is associated with the transformation of gastric cancer." (PMID 27050149, 2016). "Therefore, we thought that the abnormal expression of RNF180 in gastric cancer was associated with the aberrant mRNA transcription and protein translation events, which might be resulted from the DNA promoter methylation as the previous elucidation." (PMID 24833402, 2014). "Mounting evidence has revealed that RNF180 is irregularly expressed in numerous human cancers, including stomach cancer, pulmonary cancer, and colon cancer." (PMID 40148674, 2025). "For example, methylation detection of the RNF180/Septin9 gene has shown significant advantages in the early screening of gastric cancer." (PMID 40244232, 2025). "For instance, the RNF180/Septin9 gene methylation test is applicable for early screening of gastric cancer." (PMID 40244232, 2025). "Our study confirmed the diagnostic value of RNF180 and SFRP2 in GC, indicating that their combination can serve as a biomarker, enhancing the accuracy of gastric cancer diagnosis." (PMID 39541711, 2024). "In this study, we explored a previously neglected aspect by comprehensively investigating the potential of combining RNF180 with SFRP2 for gastric cancer diagnosis." (PMID 39541711, 2024). "Recent clinical studies have demonstrated a strong correlation between the prognosis, overall postoperative survival, lymph node metastases in patients with gastric cancer, and the RNF180 gene methylation status." (PMID 36703788, 2022). "In conclusion, the results of this study showed that the plasma RNF180 gene methylation test is more realistic and reliable in assisting gastric cancer diagnosis, which fully demonstrated its important role in gastric cancer diagnosis." (PMID 36703788, 2022). "RNF180 (ring finger protein 180), an important member of the E3 ubiquitin ligase family, act as a tumor suppressor by inhibiting the proliferation, invasion, and migration of gastric cancer cells." (PMID 35711913, 2022). "When defining a pretest probability of 0.50 for RNF180 methylation to diagnose gastric cancer, the PPP and NPP were 73% and 37%, respectively." (PMID 36703788, 2022). "According to their findings, RNF180 methylation was found in 57.89% (33/57) of plasma samples from patients with gastric cancer, but only in 23.81% (10/42) of the people in the control group." (PMID 36703788, 2022). "This is the first systematic review and meta-analysis of plasma RNF180 gene methylation in gastric cancer diagnosis." (PMID 36703788, 2022). "RNF180 is a membrane-bound E3 ubiquitin ligase, and its function as a tumor inhibitor in gastric cancer has previously been studied." (PMID 35598017, 2022). "Methylation of RNF180 (mRNF180) leads to low expression of RNF180, which is closely related to the occurrence and development of gastric cancer (GC)." (PMID 36246966, 2022). "The RNF180 methylation test had a specificity of 0.80 (95% CI: 0.72 - 0.87) in distinguishing gastric cancer patients from controls in our meta-analysis of 1531 participants from 9 research." (PMID 36703788, 2022). "It was shown that overexpression of RNF180 in gastric cancer cells can reduce STAT3 activation, attributed to increased RhoC proteasomal degradation." (PMID 32915198, 2020). "Based on our findings, we constructed the signaling pathway by which RNF180 regulates the proliferation and invasion of gastric cancer." (PMID 33082325, 2020).
gastric cancer (continued). "Our observations are consistent with previous findings in gastric cancer, in which RNF180 acts as a novel potential tumor suppressor in gastric carcinogenesis." (PMID 33553163, 2020). "RNF180 expression was found downregulated in gastric cancer and its re-expression suppressed cell growth and induced apoptosis." (PMID 33553163, 2020). "Taken together, in this study, RNF180 is characterized as a tumor suppressor to inhibit tumor metastasis by reducing RhoC in gastric cancer." (PMID 33082325, 2020). "Emerging studies have also shown that tumor suppressor genes (e.g. RNF180, Zic1) are frequently methylated, not only in gastric cancer, but also among patients with pre-malignant gastric lesions." (PMID 29348893, 2017). "CpG-116, CpG-80, CpG+97, and CpG+102 in RNF180 promoter are negatively related to the overall survival of gastric cancer patients, as revealed by multivariate analysis." (PMID 27223257, 2016). "The methylated status of the CpG+102 island should be considered the first preferred locus in the RNF180 DNA promoter for the accurate prediction of malignant biological behaviors of gastric cancer cells." (PMID 27223257, 2016). "These conclusions provided a solid basis for further studies on the biological effects of the methylation of different CpG islands in RNF180 DNA promoter on gastric cancer cell." (PMID 27223257, 2016). "This study provides an experimental basis to evaluate RNF180 promoter methylation as a biomarker for early warning and diagnosis of gastric cancer or atrophic gastritis." (PMID 27050149, 2016). "In the previous study, RNF180 transcript was identified to be specially silenced or down-regulated in gastric cancer cells and primary gastric cancer tissues, and the promoter methylation was found to directly mediate RNF180 transcription silencing in vitro." (PMID 27050149, 2016). "We previously demonstrated that the methylation of ring finger protein 180 (RNF180) DNA promoter was specific to gastric cancer tissues." (PMID 27223257, 2016). "In summary, this study focused on relationships between methylation of RNF180 promoter and gastric cancer or atrophic gastritis and the effect of H.pylori infection on RNF180 PM." (PMID 27050149, 2016). "Reports on RNF180 are scarce, though this gene was recently characterized as hypermethylated and silenced in gastric cancer with a potential function in apoptosis." (PMID 25945129, 2015). "Future research should focus on the effects of the given CpG sites contribution to the biological behaviors of gastric cancer cells and the targeted therapy to the given CpG sites of RNF180 promoter." (PMID 24833402, 2014). "We found that only few methylated CpG sites of RNF180 promoter was appropriate to predict the survival of gastric cancer." (PMID 24833402, 2014). "With the immunohistochemical staining and Western Blot detection, we detected that RNF180 protein expression in gastric cancer tissues was significantly lower than that in paired adjacent non-tumor tissues." (PMID 24833402, 2014). "RNF180 methylation was so frequently detected in gastric cancer tissue indicting that RNF180 is likely a tumor suppressor in the previous study, we decided to initially detect the methylation of RNF180 promoter with the qualitative analysis." (PMID 24833402, 2014). "The aim of this study was to detect the methylation of CpG sites of RNF180 promoter in the large scale patients with gastric cancer in order to determine which methylated CpG site of RNF180 promoter can convey worse prognosis in the China." (PMID 24833402, 2014). "At present study, we found that lower expression of RNA180 was specific in gastric cancer tissues, and the inconsistently methylated levels of RNF180 promoter were identified in the gastric cancer tissues." (PMID 24833402, 2014). "Moreover, combining the detection of RNF180 and Septin9 gene methylation with traditional tumor markers can significantly enhance the sensitivity of gastric cancer screening." (PMID 40244232, 2025).
gastric cancer (continued). "A similar study revealed the RNF180/DNMT3A/ADAMTS9 axis in gastric cancer." (PMID 39048965, 2024). "One study reported that the RS19 test is a new blood-based methylation assay for early gastric cancer detection that combines two methylated genes (RNF180 and SEPT9) in a single reaction to improve the rate for early-stage gastric cancer and gastric dysplasia detection." (PMID 38318978, 2024). "The 2023 Chinese Expert Consensus on Early Gastric Cancer Screening and Testing Techniques states that RS19 gene methylation, combined with RNF180 and Septin9, can be used for the detection of early gastric cancer, suggesting that positive subjects should undergo gastroscopy in a timely manner." (PMID 39766341, 2024). "Accordingly, it can be inferred that RNF180 methylation may be an important marker for the diagnosis of gastric cancer." (PMID 36703788, 2022). "Therefore, the RNF180 gene methylation test is an effective predictive biomarker for gastric cancer." (PMID 36703788, 2022). "RING finger domain RING finger protein 180 (RNF180) acts as a tumor suppressor in gastric cancer." (PMID 35598017, 2022). "The RNF180 mRNA levels in gastric cancer samples were relatively low." (PMID 33825941, 2021). "This highlights how directed targeting of RNF180 to gastric cancer cells could be used to block RhoC-driven activation of STAT3." (PMID 32915198, 2020). "In summary, our study reveals that RhoC is a substrate of RNF180 and that ubiquitination and degradation of RhoC by RNF180 could inhibit proliferation and invasion of gastric cancer." (PMID 33082325, 2020). "Considering the low expression of RNF180 in gastric cancer, efficiently inhibit RhoC expression might repress tumorigenesis and tumor metastasis and then improve the survival outcomes of patients, which still need further investigation." (PMID 33082325, 2020). "Therefore, these islands were not competent to comprehensively reflect the biological effects of RNF180 promoter methylation on gastric cancer cells." (PMID 27223257, 2016). "The methylated status of the CpG+97 island might also be an alternative to the methylated status of the CpG+102 island in the RNF180 DNA promoter to predict the progression of gastric cancer." (PMID 27223257, 2016). "These conclusions could help elucidate the molecular mechanisms by which RNF180 mediates gastric cancer progression." (PMID 27223257, 2016). "Furthermore, the methylation of CpG+97 island in RNF180 DNA promoter significantly contributed to the anti-apoptosis of cancer cells by changing the cell cycle and enhancing the migration capability of gastric cancer cells." (PMID 27223257, 2016). "This present study aimed to investigate whether CpG-116, CpG-80, CpG+97, and CpG+102 in RNF180 DNA promoter can moderate the malignant biological characteristics of gastric cancer cells to alter the progression of this disease." (PMID 27223257, 2016). "The methylated status of the key CpG islands of RNF180 DNA promoter may be used to predict the variations of the malignant biological characteristics of gastric cancer cells." (PMID 27223257, 2016). "We have found that the methylation status of the ring finger protein 180 (RNF180) gene may be used to predict the malignant potential of intestinal metaplasia and atypical hyperplasia of gastric mucosa and diagnose early gastric cancer (unpublished data)." (PMID 27464701, 2016). "However, we should elucidate the most intensively methylated CpG islands that induce the progression of gastric cancer in the RNF180 DNA promoter to develop precise molecular treatments for gastric cancer." (PMID 27223257, 2016). "We found, for the first time, that AMR, MSC, and HSC at particular CpG sites within RNF180 promoter region could potentially be an early indicator of gastric cancer and atrophic gastritis." (PMID 27050149, 2016). "Besides, this is first report of the CpG site methylation of RNF180 promoter to evaluate the prognosis of gastric cancer." (PMID 24833402, 2014).